NLRP3 (NLR family pyrin domain containing 3)
Diseases named in the same sentence as NLRP3 in open-access papers (continued):
Sharing a sentence is not in itself a finding about the gene and the disease.
colitis (continued). "Accordingly, deficiency of TRIM31, which would lead to stabilization of NLRP3, was demonstrated to attenuate the severity of DSS- induced colitis, in agreement with the reported protective role for NLRP3 in this model." (PMID 34356615, 2021). "For example, NLRP3 inflammasome activation in epithelial cells by GPCR signaling contributes to protection from DSS‐induced colitis." (PMID 34705319, 2021). "Here, we identified that C646, an inhibitor of histone acetyltransferase p300, exerts anti-inflammatory effects in DSS-induced colitis mice by targeting the NLRP3 inflammasome." (PMID 34322027, 2021). "In summary, there is confirmation that H2S produces its salutary actions in DSS-induced mouse colitis, at least in part by suppressing the activation of the NLRP3 inflammasome signaling pathway." (PMID 34443594, 2021). "Previously, the expression levels of mRNA encoding inflammasome components were analyzed in a murine model of colitis and significantly lower levels of inflammasome-encoding gene expression including IL18 and NLRP3 were found in response to PDE4 inhibition." (PMID 34884681, 2021). "We found that TFGU obviously inhibited the activation of NLRP3 inflammasome in CPT-11–induced colitis mice." (PMID 34025639, 2021). "In this regard, it has been reported that NLRP3 inflammasome-deficient mice show exacerbation of DSS- and 2,4,6-trinitrobenzenesulfonic acid (TNBS)-induced colitis and reduced production of IL1β60,61." (PMID 34075172, 2021). "In order to determine the potential mechanisms by Schisandrin B in model of colitis, NLRP3 inflammasome had been previously defined as the key mediators in inflammation reactions in colitis." (PMID 34628369, 2021). "In fact, administration of TiO2 microparticles to mice subjected to dextran sodium sulphate (DSS)-induced colitis has been shown to aggravate colon inflammation through the regulation of the Nlrp3 inflammasome." (PMID 33466682, 2021). "So, it is necessary to investigate the protective effect of TFGU against CPT-11–induced colitis through the NLRP3 inflammasome complex." (PMID 34025639, 2021). "To conclude, oral administration of mEVs attenuated intestinal inflammation via inhibiting TLR4-NF-κB and NLRP3 signaling pathways, restoring Treg/Th17 cell balance and the gut microbiota, thus prevented disease progression of colitis." (PMID 34373759, 2021). "NLRP3 inflammasome has been reported to be involved in a variety of inflammatory diseases including T2D, gout, and Alzheimer’s disease, as well as colitis and NASH." (PMID 33350984, 2021). "It is reported that NLRP3−/− knock-out mice showed increased acute and recurring colitis and colitis-associated cancer in the DSS and azoxymethane + DSS models, indicating NLRP3 as a tumor suppressor gene." (PMID 33821998, 2021). "These investigators observed that NLRP3 activation leads to the secretion of IL‐18, which protects the host from colitis." (PMID 34705319, 2021). "Two recent studies found that EVO ameliorated experimental colitis, at least partially, by regulating the activation of the NLRP3 inflammasome." (PMID 33808793, 2021). "For instance, the FXR agonist GW4064 exerts mild effect on colitis reduction by decreasing NLRP3 expression in LPS-induced ileum injury." (PMID 33716981, 2021). "Numerous pieces of evidence have identified that the NLRP3 inflammasome plays a pivotal role in the development and pathogenesis of colitis." (PMID 34322027, 2021). "In IBD patients carrying particular genetic abnormalities and various experimental models of colitis, excess activation of NLRP3 inflammasome intensifies the colonic inflammation." (PMID 33808793, 2021). "Collectively, various studies have demonstrated that the NLRP3 inflammasome represents a significant role in colitis pathogenesis, although the results are still questionable." (PMID 34571825, 2021). "Collectively, these findings suggest that colitis induces a NLRP3 inflammasome-dependent spatial memory deficit." (PMID 34229722, 2021).
colitis (continued). "Wogonoside protects mice from experimental colitis by inhibiting the activation of NF-κB and the NLRP3 inflammasome." (PMID 34803700, 2021). "AMPK activator GL-V9 can trigger macrophage autophagy, degrade NLRP3 inflammasomes, and have a protective effect on colitis and tumor formation in mouse colitis-related colorectal cancer." (PMID 33968087, 2021). "NLRP3 inflammasome deficiency, which comprises a deficiency of ASC, caspase-1 and NLRP3, results in a susceptibility to dextran sodium sulfate (DSS)-induced colitis, characterized by symptoms of colonic injury and enhanced inflammation." (PMID 34571825, 2021). "Absence of miR-223 exacerbates inflammation in a murine model of colitis characterized by enhanced NLRP3 inflammasome activation and IL-1β production." (PMID 34026693, 2021). "Mechanistically, the expression of NLRP3 was upregulated in the A. muciniphila group, and the protective effect of A. muciniphila in colitis depends on NLRP3 activation." (PMID 34612661, 2021). "A variety of natural products were shown to play a role in ameliorating experimental colitis, at least in part, by regulating the expression or activation of the NLRP3 inflammasome." (PMID 33808793, 2021). "We then examined the effects of colitis and NLRP3 KO on astrocyte density and polarization of astrocytic AQP4 surface expression in the cortex and hippocampus as measures of astrocytic activation and function." (PMID 34229722, 2021). "We cannot exclude the possibility that the protection conferred by NLRP3 depletion was due to attenuation of experimental colitis as depletion also decreased the histological colitis score." (PMID 34229722, 2021). "GL-V9 was found protected against colitis and tumorigenesis via triggering autophagy to degrade the NLRP3 inflammasome." (PMID 34571825, 2021). "The association between GPBAR1 and NLRP3 has also been demonstrated, but most studies have mainly confirmed the effect of GPBAR1 on the NLRP3 inflammasome in the context of neuroinflammation, colitis, pancreatitis and nonalcoholic steatohepatitis (NASH)." (PMID 35095513, 2021). "Histological score was significantly lower in DDS-treated NLRP3 KO mice than WT mice (t = 2.46, P < 0.05), indicating that colitis was NLRP3-dependent." (PMID 34229722, 2021). "Data from patients or animals with NLRP3 hyper-activity provide a similar controversial picture for the role of NLRP3 in colitis." (PMID 34344313, 2021). "Previous studies have shown that the NLRP3 inflammasome exacerbates the severity of acute colitis induced by DSS and inherited spontaneous colitis." (PMID 34335248, 2021). "Numerous studies have suggested that the NLRP3 inflammasome is a potential target for the treatment of colitis." (PMID 34322027, 2021). "Some studies have shown that NLRP3 inflammasome-induced IL1β aggravates colitis, and inhibition of NLRP3 inflammasome activity has been proposed as a therapeutic strategy for treatment of colitis." (PMID 34075172, 2021). "SCFA acetate binding to metabolite‐sensing receptors GPR43 and/or GPCR109A has been shown to mediate a protective effect against colitis and drive activation of NLRP3 inflammasome in epithelial cells, showing caspase 1 activation and secretion of IL‐18." (PMID 33682108, 2021). "Another study reported that the inhibition of NLRP3 inflammasome assembly in macrophages was responsible for the preventive effect of arctigenin against CAC in patients with colitis." (PMID 34571825, 2021). "On the one hand, administration of Schisandrin B suppressed NLRP3 protein expression in colon tissue of DSS induced colitis mice model." (PMID 34628369, 2021). "Collectively, these results identify the NLRP3 inflammasome as a potential therapeutic target for AD and other neuroinflammatory disorders exacerbated by colitis." (PMID 34229722, 2021).
colitis (continued). "We first compared histological signs of colitis, brain expression levels of the NLRP3 inflammasome, and accumulation of downstream pro-inflammatory factors between WT and NLRP3 KO mice under control conditions and following oral DSS administration for 4 weeks." (PMID 34229722, 2021). "As revealed by these results, AMPK was the target spot of Schisandrin B on NLRP3 inflammasome in colitis model." (PMID 34628369, 2021). "Taken together, these results suggest that the therapeutic effect of A. muciniphila in colitis depends on NLRP3." (PMID 34612661, 2021). "In the present study, we have found that C646 plays an anti-inflammatory role in the DSS-induced colitis model by targeting the NLRP3 inflammasome." (PMID 34322027, 2021). "In previous studies, NLRP3 inflammasome suppression with DMF has been reported in diabetes-associated vascular complications and dextran sulfate sodium-induced colitis." (PMID 34858398, 2021). "Collectively, these results indicated that DSS-induced colitis and neural NLRP3 inflammasome activity impaired glymphatic clearance, while NLRP3 inflammasome suppression mitigated this effect." (PMID 34229722, 2021). "NLRP3(−/−) mice exhibited resistance to colon mucosal damage and relieved colitis in the DSS or TNBS (2,4,6-trinitrobenzene sulfonic acid) model, and IL-10(−/−) model, with reduced mortality." (PMID 34294138, 2021). "Earlier studies have documented that intervention with fraxinellone ameliorated colitis severity in murine models via suppression of NLRP3 inflammasome activation." (PMID 34443594, 2021). "In summary, our findings for first time indicated that Schisandrin B reduces the epithelial cells injury of colitis through regulating pyroptosis by AMPK/Nrf2/NLRP3 inflammasome." (PMID 34628369, 2021). "Intriguingly, Berberine inhibits NLRP3 activation in DSS-induced colitis in a Rev-erbα-dependent manner." (PMID 33716981, 2021). "In conclusion, A. muciniphila alleviates DSS-induced acute colitis by NLRP3 activation, which enriches the mechanism and provides a new prospect for the probiotic-based treatment of colitis." (PMID 34612661, 2021). "Activation of NLRP3 inflammasome in the colon has been shown to have both protective and detrimental effects in different colitis studies." (PMID 33682108, 2021). "Taken together, these data suggested that C646 inhibits NLRP3 inflammasome activation in the DSS-induced colitis model." (PMID 34322027, 2021). "Treatment with the NLRP3-dependent procaspase 1, IL-1β, and the IL-18 inhibitor Fclla-2 can reduce colon inflammation in mice, and the NLRP3 inflammasome can initiate and promote the inflammatory response in colitis." (PMID 34408782, 2021). "To further verify the relationship between A. muciniphila and NLRP3 expression in colitis, we tested the expression of NLRP3 in the DSS-induced colitis model." (PMID 34612661, 2021). "In combination with NLRP3 activation, we wondered if there is relevance among A. muciniphila, NLRP3, and colitis." (PMID 34612661, 2021). "Strikingly, NLRP3 inflammasome is induced in dextran sulfate sodium (DSS)-induced colitis mouse model." (PMID 33716981, 2021). "Among UC patients and mice with DSS-induced colitis, the numbers of NLRP3 inflammatory complexes are increased significantly." (PMID 34462641, 2021). "On the other hand, other inhibitors have attenuated the effects of colitis through indirect interactions with the NLRP3 inflammasome." (PMID 32456012, 2020). "Other studies on the NLRP3 inflammasome that used the DSS-induced colitis model have reported mixed findings (i.e., exacerbation and alleviation of colitis)." (PMID 33227973, 2020). "Andrographolide (Andro), a small molecule, protects mice against colitis-induced colon carcinogenesis by activating mitophagy, suppressing the NLRP3 inflammasome, and reducing IL1B secretion." (PMID 32630319, 2020). "By contrast, there are many reports showing that NLRP3 has a function of protecting against colitis." (PMID 33143375, 2020).
colitis (continued). "Some studies reported that NLRP3 inflammasome activation was detrimental to the progression of colitis in a DSS-induced mouse model." (PMID 33143375, 2020). "The NLRP3 inflammasome, has been analyzed extensively in its contribution to colitis and is considered to be important in the development of therapeutic strategies." (PMID 33143375, 2020). "IL-10 signaling is protective against colitis through the regulation of the NLRP3 inflammasome and IL-1β secretion." (PMID 32630319, 2020). "The small molecule andrographolide prevented colitis progression and colon cancer development by suppressing the activation of NLRP3 inflammasomes." (PMID 32703253, 2020). "The platelet-activating factor receptor regulates colitis-induced lung inflammation via the NLRP3 inflammasome." (PMID 33143375, 2020). "Confirming previous results, Rev-erbα-deficient mice were found to display increased activation of the NLRP3 pathway which accounted for the severe phenotype, whereas pharmacological Rev-erb activation attenuated colitis in vivo." (PMID 32849554, 2020). "Mitochondrial, as the major site of ROS production in most mammalian cells, plays a central role in colitis and NLRP3 inflammasome activation." (PMID 32950971, 2020). "Rev-erbα activation inhibits fulminant hepatitis, colitis, Myocardial I/R, and lung infection in an NLRP3 dependent manner." (PMID 32630319, 2020). "We next focused on the role of the NLRP3 inflammasome in the exacerbated colitis in Slco2a1−/− mice." (PMID 32184453, 2020). "In conclusion, we unravel a critical role of the NLRP3 inflammasome in Cg-induced pro-inflammatory cytokines production and colitis, which is an important discovery on the pro-inflammatory properties of this sulfated polysaccharide for pre-clinical studies." (PMID 32894139, 2020). "In summary, our study demonstrated that DSC alleviated DSS‐induced colitis by inhibiting Nox4‐mediated NF‐κB and NLRP3 inflammasome activation." (PMID 32945118, 2020). "Meanwhile, it has been reported that some members of the microbiota can protect against colitis by suppressing NLRP3 activation." (PMID 33143375, 2020). "NLRP3 KO mice were found to be susceptible to DSS- and 2,4,6-trinitrobenezene sulfonic acid-induced experimental colitis and had reduced levels of IL-1β, IL-10, and TGF-β." (PMID 33143375, 2020). "As for wogonoside (12.5, 25 or 50 mg/kg), its application inhibits the activation of NF-κB-induced NLRP3 inflammasomes in DSS-induced colitis and colitis-associated tumorigenesis in mice." (PMID 32063999, 2020). "Kynurenic acid/GPR35 axis limits NLRP3 inflammasome activation and exacerbates colitis in socially stressed mice." (PMID 33143375, 2020). "Dextran sulfate sodium (DSS)-induced severe colitis in mice has been suggested to be due to the activation of the NLRP3 inflammasome and release of mature IL-1β." (PMID 33143375, 2020). "Zhang’s lab reported that evodiamine prevented dextran sulfate sodium-induced murine experimental colitis via the regulation of NF-κB and NLRP3 inflammasome." (PMID 33240089, 2020). "The AhR/Nrf2 signals produced by cardamonin would then activate NQO1, which has inhibitory effects in NLRP3 inflammasome priming, which lead to a reduction in pro-inflammatory cytokines and produce anti-colitis effects." (PMID 32456012, 2020). "For instance, Nlrp3-/-, Asc-/-, and caspase-1-/- mice were observed to be highly susceptible to DSS-induced colitis." (PMID 33119702, 2020). "Although the contribution of NLRP3 for Inflammatory Bowel Disease is controversial, there is evidence suggesting its pro-inflammatory role in different experimental models of colitis." (PMID 32894139, 2020). "Soy isoflavones were shown to ameliorate, while 1,25(OH)2D3 and flavonoid VI-16 were shown to protect against experimental colitis by inhibiting NLRP3 inflammasome activation." (PMID 33143375, 2020).
colitis (continued). "The colitis severity score and neutrophils infiltration showed a significant reduction in Nlrp3−/−, Pycard−/− and Casp1/11−/− mice compared to C57BL/6 mice." (PMID 32894139, 2020). "The presence of dietary fiber and SCFAs protects against DSS-induced colitis via NLRP3 activation in colonic epithelial cells." (PMID 33143375, 2020). "Circadian oscillations of NLRP3 signaling is lost in models of clock disruption, contributing to the development of peritonitis, hepatitis, or colitis." (PMID 32849554, 2020). "In these studies, it was observed that the greatest susceptibility to the development of colitis in ASC-/-, NLRP6-/-, NLRP1-/-, NLRP3-/-, AIM2-/- or caspase-1-/- mice was related to a decrease in IL-18 levels." (PMID 32545788, 2020). "We used qRT-PCR and Western blotting assays and demonstrated that SA reduced the activation of the NLRP3 inflammasome and attenuated intestinal permeability by enhancing the expression of ZO-1, occludin, and claudin-1 in colitis mice." (PMID 33312339, 2020). "Taken together, these data supported that DSC alleviated experimental colitis at least in part through inhibiting Nox4‐mediated NF‐κB and NLRP3 inflammasome activation." (PMID 32945118, 2020). "Our results suggest that GPA inhibits NLRP3 inflammasome activation through increasing AMPK phosphorylation to suppress ROS, and can be applied in the prevention of colitis through targeting NLRP3." (PMID 32950971, 2020). "Overall, these results suggested that NLRP3 expression is critical for protection against DSS-induced colitis by GPA." (PMID 32950971, 2020). "Promisingly there are successful therapeutic agents determined to be AhR agonists that treat TNBS- and DSS-induced colitis via the NLRP3 inflammasome but they are still far from many." (PMID 32456012, 2020). "There is still a disparity in the results from many studies that describe the role NLRP3 plays on colitis as a protective or detrimental one." (PMID 32456012, 2020). "MCC950, the most potent and specific inhibitor of NLRP3, has proven efficacy in many mouse models of NLRP3-driven diseases, such as colitis, NASH, Alzheimer’s disease and other afflictions." (PMID 32312957, 2020). "At 20 day after Cg treatment, high-resolution live colonoscopy analyses revealed that Nlrp3−/−, Pycard−/− and Casp1/11−/− were protected from Cg-induced colitis." (PMID 32894139, 2020). "Several in vivo studies have investigated the effects of pharmacological inhibition or the gene deletion of the NLRP3 inflammasome components in colitis animal models." (PMID 32545788, 2020). "Our findings pointed out a crucial role for the canonical NLRP3 inflammasome in Cg-induced colitis in mice." (PMID 32894139, 2020). "Taking these findings together, it can be considered that the NLRP3 inflammasome in macrophages was autocrinally activated by the elevated concentrations of PGE2, leading to exacerbation of colitis in Slco2a1-deficient mice." (PMID 32184453, 2020). "In an ulcerative colitis (UC) model, palmatine, a herb-derived isoquinoline alkaloid, has protective effects on dextran sulfate sodium (DSS)-induced colitis by enhancing mitophagy, which inhibits NLRP3 inflammasome activation." (PMID 32630319, 2020). "Many studies have shown that the NLRP3 inflammasome plays an important role in colitis, but the interpretations of the results are still controversial." (PMID 33143375, 2020). "Studies that used a mouse model of oxazolone-induced colitis or a challenge with the attaching/effacing intestinal pathogen Citrobacter rodentium demonstrated exacerbated colitis and increased bacterial colonization and dispersion in Nlrp3−/− mice." (PMID 33227973, 2020). "In contrast, sinapic acid was shown to reduce the generation and mRNA expression levels of some inflammatory cytokines (TNF-α, IL-1β, IL-6, IL-8, IL-17α, and IFN-γ) and reduce the activation of the NLRP3 inflammasome in the colons of colitis mice." (PMID 33312339, 2020).